HGF (hepatocyte growth factor)
Diseases named in the same sentence as HGF in open-access papers (continued):
Sharing a sentence is not in itself a finding about the gene and the disease.
periodontitis (20 papers, 2012 to 2025). An acute or chronic inflammatory process that affects the tissues that surround and support the teeth. "Future studies should validate causality through fecal transplantation and delineate how HGF-driven gut leakage propagates multi-organ dysfunction, ultimately advancing precision interventions for periodontitis-associated comorbidities." (PMID 40427685, 2025). "Our findings revealed that HGF significantly altered microbial diversity and composition, which were linked to inflammation and bone metabolism during periodontitis." (PMID 41154794, 2025). "Elevated levels of HGF in oral rinse and gingival cervical fluids (GCFs) were associated with the severity of periodontitis." (PMID 41154794, 2025). "Meanwhile, HGF diminished the enrichment of Faecalibaculum and g_norank_f__Erysipelatoclostridiaceae in the context of periodontitis, which are associated with anti-inflammatory properties." (PMID 40427685, 2025). "In summary, our data point towards the relevance of HGF in periodontitis-associated tissue remodeling and suggest the use of HGF neutralizing antibody treatment as a novel therapeutic approach." (PMID 34128105, 2021). "In periodontitis, a positive association has been described between concentrations of HGF in saliva and alveolar bone loss." (PMID 34128105, 2021). "HGF is also a healing factor, with cytoprotective effects in conditions associated with inflammatory diseases, including periodontitis." (PMID 26670567, 2015). "Exceptionally, 3 independent studies demonstrated significant association of salivary HGF with periodontitis which is consistent with similar data analysing GCF." (PMID 24944840, 2014). "The pathogenic microorganism Porphyromonas gingivalis is associated with periodontitis and stimulates the production of HGF by gingival fibroblasts." (PMID 25389376, 2014). "Hepatocyte growth factor (HGF), a novel regulator of inflammatory bone loss in periodontitis, may serve as a critical communicator between oral infection and distal intestinal pathology." (PMID 40427685, 2025). "Notably, HGF also increased the enrichment of the periodontitis-associated pathogens (e.g., Desulfovibrio and Streptococcus) in the gut." (PMID 40427685, 2025). "Based on these observations, we hypothesize that HGF exerts stage-specific effects on periodontitis, which are associated with distinct changes in microbiota at different stages." (PMID 41154794, 2025). "Given that PAFs constitute a major source of HGF in periodontitis, HGF may represent a hallmark of pathologically activated or disease-associated fibroblasts." (PMID 34128105, 2021). "Further studies may help establish the association between the severity of periodontitis and the HGF levels in saliva and GCF." (PMID 25389376, 2014). "An association between HGF and periodontitis has been previously reported." (PMID 25389376, 2014). "Our results attested that the enrichment of Patescibacteria, Proteobacteria, Campilobacterota, and Cyanobacteria was responsible for differences in abundance at the phylum level in HGF-Tg mice with periodontitis." (PMID 40427685, 2025). "In this study, we examined how HGF affects bacteria attached to ligatures placed around teeth in mice with periodontitis." (PMID 41154794, 2025). "The LEfSe analysis further revealed alterations in the oral microbiota of WT and HGF-Tg mice with periodontitis compared with controls." (PMID 41154794, 2025). "To address the gap, we employed HGF-Tg mice with ligature-induced periodontitis to investigate the overlooked role of HGF in modulating gut ecology and barrier function." (PMID 40427685, 2025). "Here, we investigated the impact of HGF on the periodontal microbiome during periodontitis progression." (PMID 41154794, 2025). "Our study demonstrated that periodontitis reduced α-diversity in both WT and HGF-Tg mice, and HGF elevated α-diversity in the late stage of periodontitis." (PMID 41154794, 2025).
periodontitis (continued). "Clinical studies have reported elevated levels of HGF in the gingival crevicular fluid (GCF) of patients with periodontitis, where its concentration correlates with disease severity." (PMID 40427685, 2025). "In both WT and HGF-Tg mice, α-diversity significantly decreased on days 7 and 28 compared to day 0 (p < 0.01), indicating a reduction in microbial diversity as periodontitis developed." (PMID 41154794, 2025). "To delve into the impact of periodontitis and HGF on the composition of gut microbiota, we analyzed the abundance of gut microbiota in all samples." (PMID 40427685, 2025). "Elevated serum levels of D-lactate, LPS, and DAO in HGF-Tg mice with periodontitis collectively demonstrated that HGF exacerbated intestinal hyperpermeability, enabling microbial products to translocate systemically." (PMID 40427685, 2025). "More importantly, the concentrations of serum LPS and D-lactate were significantly higher in the HGF-Tg mice than that in the WT mice during periodontitis." (PMID 40427685, 2025). "In our previous study, we found that HGF was upregulated in mice with periodontitis by aggravating the progress of periodontitis via the IL-17/RANKL/TRAF6 pathway using HGF high-expression transgenic (HGF-Tg) mice." (PMID 40427685, 2025). "Our preliminary findings revealed that HGF played a protective role in the early stage of experimental periodontitis but exacerbated the bone destruction and inflammation in the late phase." (PMID 41154794, 2025). "The serum levels of LPS and D-lactate were elevated in both the WT and HGF-Tg mice with periodontitis compared with the controls." (PMID 40427685, 2025). "Our study bridges these gaps by demonstrating that HGF exacerbates periodontitis-induced gut barrier dysfunction through microbiota–immune crosstalk, thereby positioning HGF as a novel systemic amplifier of oral–gut axis dysregulation." (PMID 40427685, 2025). "This study investigates how HGF overexpression modulates the gut microbial ecosystem and intestinal barrier integrity in a transgenic periodontitis model." (PMID 40427685, 2025). "The changes in certain bacterial taxa and predicted inflammatory pathways showed different trends between the two stages, consistent with the different impact of HGF on periodontitis." (PMID 41154794, 2025). "Our results demonstrated that HGF further upregulated the intestinal expression of NOD2 to alter the gut immune barrier when periodontitis occurred." (PMID 40427685, 2025). "The results demonstrated that HGF increased gut permeability in the context of periodontitis, as evidenced by elevated serum levels of D-lactate and LPS compared to wild type (WT) mice." (PMID 40427685, 2025). "This study aims to elucidate the impact of HGF on the microbiota of ligatures using ligature-induced periodontitis in wild-type (WT) and HGF high-expression transgenic (HGF-Tg) mice." (PMID 41154794, 2025). "In this study, we examined the ligature microbiota of HGF-Tg mice during the early and late stages of experimental periodontitis." (PMID 41154794, 2025). "Our study established HGF as a potential host-derived mediator of oral–gut axis dysregulation in periodontitis." (PMID 40427685, 2025). "Microbial functions, particularly metabolic pathways, were significantly altered by HGF when periodontitis occurred." (PMID 40427685, 2025). "Specifically, we aimed to decipher how HGF overexpression altered gut microbiota composition (with a focus on periodontitis-related pathobionts) and assess gut barrier compromise at mechanical, immunological, and functional levels." (PMID 40427685, 2025). "This aligns with the emerging paradigm wherein periodontitis acts as a “remote driver”, not only through direct gut microbial dissemination but also via host-derived mediators like HGF that amplify gut barrier fragility." (PMID 40427685, 2025).
periodontitis (continued). "In summary, the sequential MI treatment MIM-seq displayed cellular anti-inflammatory effects, reducing secreted PGE2 and IL-6 levels and restoring collagen content in an in vitro model of hGF periodontitis." (PMID 37445663, 2023). "In conclusion, telocytes express HGF and, based on the ScRNA-seq analysis, are the only cells that produce this signal in periodontitis." (PMID 36193890, 2022). "We show that telocytes are quiescent in homeostasis; however, they proliferate and serve as a major source of HGF in periodontitis." (PMID 36193890, 2022). "We performed scRNA-seq and lineage tracing to identify telocytes and macrophages in mouse periodontium in homeostasis and periodontitis and carried out hepatocyte growth factor (HGF) signalling inhibition experiments using tivantinib." (PMID 36193890, 2022). "We observed that when tivantinib was administered to mice with ligature-induced periodontitis, Arg1+ cell numbers significantly decreased, indicating that inhibition of the HGF-Met signalling interaction in macrophages blocks their polarisation." (PMID 36193890, 2022). "We show that quiescent telocytes located near blood vessels are activated in periodontitis and regulate macrophages via the hepatocyte growth factor (HGF)/Met signalling pathway." (PMID 36193890, 2022). "In mouse ligature-induced periodontitis, our RNA-seq cell–cell communication analysis identified macrophages as a target of HGF signalling from telocytes." (PMID 36193890, 2022). "Collectively, our study demonstrates for the first time that telocytes increase in number in periodontitis and communicate with immune cells to positively regulate periodontitis via HGF." (PMID 36193890, 2022). "These cells, telocytes, are in a quiescent state in normal periodontal tissue unless challenged by periodontitis whereupon they increase in number and secrete HGF." (PMID 36193890, 2022). "Clinical and experimental studies suggest that hepatocyte growth factor (HGF) is involved in the dysregulated fibroblast–epithelial cell interactions in periodontitis." (PMID 34128105, 2021). "We and others further showed that HGF concentration is upregulated in GCF of periodontitis patients." (PMID 34128105, 2021). "We also demonstrated that PAFs are characterized by enhanced HGF gene expression, suggesting PAFs as a major source of HGF production in periodontitis." (PMID 34128105, 2021). "Taking into account the concentration levels of HGF, alone, subjects with HGF levels > 0.470 ng/ml were classified with periodontitis condition with an accuracy of 88.2%." (PMID 33742017, 2021). "In our study, LBP and HGF exhibited more than ~ 5 × higher concentration levels in periodontitis than in health groups, in line with the literature." (PMID 33742017, 2021). "Here, we further addressed HGF as a potential molecular target in an experimental model of periodontitis using a unique human primary cells and 3D co-culture system." (PMID 34128105, 2021). "Of importance, HGF levels were found to correlate with established predictors of periodontitis such as probing depth (PD), gingival index (GI), bleeding on probing (BOP), and bone resorption." (PMID 34128105, 2021). "We also transplanted HGF-modified hDPSCs for treating periodontitis in miniature pigs to evaluate the role of HGF in periodontal tissue regeneration." (PMID 26670567, 2015). "We generated periodontitis lesions in miniature swine, and then transplanted hDPSCs or HGF-hDPSCs into the defects." (PMID 26670567, 2015). "The present study investigated the feasibility of transplanting hDPSC/HGF-hDPSCs and hDPSC/HGF-hDPSC sheets for treating periodontitis in a large animal model." (PMID 26670567, 2015). "A number of studies demonstrated that HGF levels were elevated in patients with chronic periodontitis." (PMID 26670567, 2015).
periodontitis (continued). "Our data demonstrated that hDPSC/HGF-hDPSC injections and hDPSC/HGF-hDPSC sheets provided appropriate therapy for periodontitis, by inducing significant periodontal bone regeneration and soft tissue recovery." (PMID 26670567, 2015). "During inflammatory conditions, such as periodontitis, HGF production by oral fibroblasts is enhanced by various molecules that are induced during inflammation." (PMID 25389376, 2014). "Hepatocyte growth factor (HGF) production by oral fibroblasts is enhanced by various molecules that are induced during inflammatory conditions including periodontitis." (PMID 25389376, 2014). "The HGF concentration in the gingival crevicular fluid (GCF) of patients with periodontitis is approximately 10-fold higher than that of healthy subjects." (PMID 25389376, 2014). "HGF plays an important role in the progression of periodontitis, by stimulating intense growth of epithelial cells and preventing regeneration of connective tissue attachments." (PMID 25389376, 2014). "In periodontitis, the production of HGF is induced by various factors derived from the host, such as inflammatory cytokines and bacterial components." (PMID 25389376, 2014). "Interestingly, our prior findings also indicated that HGF exerted divergent regulatory effects on the IL-17/RANKL/OPG axis in different stages of periodontitis." (PMID 41154794, 2025). "The specific mechanism by which periodontitis is altered by microbes in the presence of HGF remains unclear." (PMID 41154794, 2025). "We have previously reported that hepatocyte growth factor (HGF) could mitigate early-stage experimental periodontitis but exacerbate the condition in its late stage." (PMID 41154794, 2025). "Interestingly, specific microbial genera, such as Lactobacillus, exhibited opposing trends between the two disease stages of HGF-Tg mice, aligning with the different effects of HGF on periodontitis progression." (PMID 41154794, 2025). "Additionally, the PICRUSt2 analysis depicted distinctly contrasting bacterial functions altered by HGF when periodontitis occurred, particularly in metabolic functions." (PMID 40427685, 2025). "Some microorganisms like g_Desulfovibrio may play a role in gut barrier disorder in HGF-Tg mice with periodontitis." (PMID 40427685, 2025). "Moreover, HGF-Tg mice with periodontitis exhibited significant dysbiosis of gut microbiota, with reduced levels of probiotics (e.g., Faecalibaculum)." (PMID 40427685, 2025). "Furthermore, the pathway involved in o-antigen biosynthesis, an essential component of LPS, was more highly enriched in the HGF-Tg mice with periodontitis, which aligned with the elevated serum level of LPS." (PMID 40427685, 2025). "Notably, changes in certain flora, including genus_Lactobacillus, showed contrasting trends during the two disease periods of HGF-Tg mice, consistent with the different effects of HGF on periodontitis progression." (PMID 41154794, 2025). "In addition, HGF also diminished the abundance of the FoxO signaling pathway at the early stage of periodontitis." (PMID 41154794, 2025). "In addition, HGF further significantly facilitated the downregulation of occludin in the context of periodontitis." (PMID 40427685, 2025). "While HGF is reported to enhance TJ integrity in isolated intestinal repair models, our findings revealed a paradoxical disruptive role in the gut milieu when periodontitis occurred." (PMID 40427685, 2025). "Beyond its role in periodontitis, HGF is a double-edged sword in intestinal structure and function." (PMID 40427685, 2025). "The ability of telocytes to influence macrophage polarization via the HGF-Met pathway from an inflammatory (M1) state toward a tissue-remodeling phenotype (M1/M2) in a preclinical model of periodontitis hints at the potential of telocyte-macrophage interactions in IBD and its associated fibrosis." (PMID 39872845, 2024). "On the other hand, hepatocyte growth factor was increased in saliva of smokers with periodontitis." (PMID 35676670, 2022).
periodontitis (continued). "The activation of HGF/Met signalling pathway or the exogenous use of activated telocytes may be a promising therapeutic measure against periodontitis." (PMID 36193890, 2022). "At an HGF cutoff value of 0.613 pg/ml, this biomarker alone could most likely differentiate gingivitis from periodontitis at an accuracy of 79.5%." (PMID 33742017, 2021). "Antagonizing HGF signaling by a neutralizing antibody may represent a novel approach for periodontitis treatment." (PMID 34128105, 2021). "We hypothesized that HGF signaling-mediated cellular interactions might impact on periodontitis progression." (PMID 34128105, 2021). "Our data might pave the way for HGF antagonism as a novel therapeutic approach against periodontitis." (PMID 34128105, 2021). "Our study highlights a potential role of HGF in periodontitis." (PMID 34128105, 2021). "Here, we sought to address whether HGF might serve as a therapeutic target utilizing a state-of-the art in vitro co-culture system as an experimental model of periodontitis." (PMID 34128105, 2021). "Thus, it is possible that the TGF-β pathway is also functionally involved in the development of periodontitis and is connected to HGF signaling." (PMID 34128105, 2021). "Concentrations of HGF at periodontitis sites have been reported to be almost twice that of healthy sites, whilst HGF concentrations in GCF are approximately 8 times higher than serum concentrations, suggesting that much of the HGF present in GCF is produced by gingival fibroblasts." (PMID 30041453, 2018). "HGF is a well-known serum marker for various diseases, including periodontitis." (PMID 25389376, 2014). "The significantly higher levels of HGF in smokers with periodontitis might be due to the adverse effects of smoking on the periodontium." (PMID 25389376, 2014). "A high level of HGF in the GCF was reported in patients with periodontitis." (PMID 25389376, 2014). "In addition, gut villous morphology disorder was observed in HGF-Tg mice with periodontitis." (PMID 40427685, 2025). "Our results reveal the source of HGF signals in periodontal tissue and provide new insights into the function of telocytes in regulating macrophage behaviour in periodontitis through HGF/Met cell signalling, which may provide a novel approach in periodontitis treatment." (PMID 36193890, 2022). "Therefore, the role of telocytes in periodontitis may not only be the regulation of macrophages through HGF/Met signalling pathway but also through angiogenesis." (PMID 36193890, 2022). "Therefore, downregulation of HGF in H-GMSCs may be important for the promotion of inflammation in the early phase of periodontitis." (PMID 35408871, 2022). "Taken together with our observation that antagonizing HGF results in alleviated collagen degradation in 3D co-cultures, these data implicated that HGF signaling drives expression changes in a subset of genes that are involved in ECM turnover underlying the pathogenesis of periodontitis." (PMID 34128105, 2021). "In terms of function, HGF is known to be involved in dental development but, significantly, HGF is secreted by gingival fibroblasts and HGF secretion is regulated by cytokines and bacterial products; it has been hypothesised that HGF may mediate epithelial apical migration in periodontitis." (PMID 24944840, 2014). "HGF also diminished the protein level of occludin and upregulated NOD2 expression in mice with periodontitis." (PMID 40427685, 2025). "Previous studies demonstrated that hepatocyte growth factor (HGF) is secreted by gingival fibroblasts and is abundant in gingival crevicular fluid (GCF) of periodontitis patients, indicating its clinical relevance." (PMID 34128105, 2021). "For discriminating gingivitis vs periodontitis groups, the predictor variables resulting from the CART analysis included HGF, TIMP-1, MMP-9/TIMP-1 ratio and OPG." (PMID 33742017, 2021).